CRP (C-reactive protein)
Diseases named in the same sentence as CRP in open-access papers (continued):
Sharing a sentence is not in itself a finding about the gene and the disease.
COVID-19 (continued). "From the experience with CRP apheresis in myocardial infarction, we concluded that the earliest possible time for the use of CRP apheresis should be aimed for, which we assume to be in the first 72 h after the onset of severe COVID-19." (PMID 35407564, 2022). "In the circulation of patients with COVID-19, IL-6 reaches its peak at advanced stages, on average after the second week of disease, and, notably, this increase is accompanied by peak concentrations of IL-10 and CRP." (PMID 35340805, 2022). "Moreover, compared to mild and asymptomatic patients, blood urea, serum creatinine, AST, first and second ESR, CRP, ferritin, and D-dimer levels were significantly increased in the severe COVID-19 subjects (p < 0.001)." (PMID 36560587, 2022). "In addition, similarly to our findings, CRP, IL-6, ferritin, D-dimer, LDH, and troponin have been identified as severity and prognostic markers of COVID-19-associated MIS." (PMID 35935801, 2022). "Surprisingly, our analysis underlined the fact that while the FMD continues to be correlated to COVID-19 severity after 3 months, CRP measurement did not maintain its association with disease severity (data not shown)." (PMID 35407382, 2022). "The most common laboratory abnormalities identified in patients with COVID-19 include decreased albumin and lymphocyte count and elevated C-reactive protein (CRP), lactate dehydrogenase (LDH), erythrocyte sedimentation rate (ESR), aspartate transaminase (AST), and alanine transaminase (ALT)." (PMID 36570594, 2022). "Thus, we plotted the levels of NP, CRP, and IL-6 against the days after onset in the COVID-19 patients." (PMID 35529699, 2022). "In COVID-19, not only do factors such as smoking, hypertension, diabetes mellitus, chronic obstructive pulmonary disease, physical frailty, and C-reactive protein impact the severity/mortality of COVID-19, but also the components of DO, such as loss of grip strength and sarcopenia." (PMID 35955411, 2022). "Clinical manifestation such as PCT could indicate the progression of COVID-19 and higher serum PCT and CRP levels were observed in critical patients with COVID-19." (PMID 35168674, 2022). "Presently, we witnessed an increased level of neutrophils, procalcitonin, WBC, EST, and AST and a decreased level of albumin in COVID-MRSA pneumonia patients, whereas LDH, D-dimer, ferritin, troponin-I, CK, and CRP were increased in both COVID-MRSA as well as in COVID-19 patients." (PMID 35997388, 2022). "Although a significant difference in CRP increase was indicated by univariate analysis in primary and validation cohorts, it was not an independent predictor for the identification of clinical condition of COVID-19 in this study." (PMID 35078525, 2022). "Our clinical observations regarding the here presented seven patients support the hypothesis that CRP is a candidate to be therapeutically targeted in the early stage of severe COVID-19." (PMID 35407564, 2022). "Elevated D-Dimer, CRP levels, and arterial and venous thromboembolism were observed in a case series of severe COVID-19 patients, indicating that TCZ could mask the inflammatory markers while not decreasing the risk of thrombotic events." (PMID 35203844, 2022). "Further research is needed to ascertain whether immune dysregulation in HIV may result in an exaggerated immune response to COVID-19, resulting in higher CRP levels." (PMID 35725387, 2022). "We aimed to investigate whether platelet-to-CRP ratio (PC ratio) could predict the severity of COVID-19 and multi-organ injuries." (PMID 35592303, 2022). "Moreover, these laboratory variables are of great interest in COVID-19 patients because COVID-19 infection causes cytokine storm leading to elevated inflammatory markers, such as ferritin, LDH, CRP, and IL-6." (PMID 35562677, 2022).
COVID-19 (continued). "This novel association between galectin-3 and CRP has not been reported in viral infection, much less in COVID-19 but it suggests the utility of this molecule in detecting the inflammatory state of patients upon hospital arrival." (PMID 35115644, 2022). "Additionally, researchers from the Wuhan region have shown that a neural net based on C-reactive protein, lactate dehydrogenase and lymphocyte count can predict mortality in Chinese COVID-19 patients." (PMID 36248875, 2022). "In contrast to the current study, in which CRP levels were lower in the Japanese compared with the German cohort, another study on the influence of ethnicity in COVID-19 patients revealed that CRP values in Asians/Indians and Hispanics were higher than in Whites." (PMID 36289811, 2022). "The other inflammatory markers were elevated in patients during the acute phase of COVID-19, including CRP levels (56mg/L vs. 12mg/L, p-value < 0.001), IL-6 (49pg/mL vs. 17pg/mL, p-value < 0.001), fibrinogen (5.1g/L vs. 3.7g/L, p-value < 0.001), and D-dimers (331ng/mL vs. 262ng/mL, p-value < 0.001)." (PMID 35160114, 2022). "Our clinical observations regarding the here presented seven patients support the hypothesis that CRP should be therapeutically targeted in COVID-19." (PMID 35407564, 2022). "CRP levels further correlate with computed tomography (CT) findings in COVID-19 patients." (PMID 35407379, 2022). "CRP is usually elevated in the COVID-19 patients as a result of ongoing inflammation." (PMID 35246169, 2022). "The first study included COVID-19 patients with CRP > 60 mg/L, and the authors observed decreased CRP, fibrinogen, creatinine, and body temperature, and increased lymphocyte and platelet counts and alanine-transferase activity in all groups of patients 7–10 days after the start of therapy." (PMID 36001576, 2022). "In exploratory analysis of laboratory findings at the time of suspecting COVID-19 myocarditis, mean fold elevation in troponin above normal limit (100.84), CRP (80 mg/L), lactate (2.79 mmol/L), D-dimer (3,775 ng/mL), ferritin (8,355 ng/mL), and procalcitonin (23 ng/mL) were all markedly elevated." (PMID 35433282, 2022). "Comparison of plasma FABP2 levels with other circulating metabolites and patient clinical data in the more severe COVID-19 group showed the strongest negative associations (i.e. high level when FABP2 is low) with CRP, Il–6 and zonulin." (PMID 36335131, 2022). "However, significant differences were observed in inflammatory marker values: CRP showed a notable raise in the pre-pandemic group (p = 0.027), while ferritin levels were higher in the COVID-19 group (p = 0.0001)." (PMID 36553203, 2022). "Receiver operating characteristic analyses were performed to determine the area under the curve (AUC), optimal cut-off value, sensitivity and specificity values of age, ADMA, SDMA, L-NMMA, NLR, CRP, D-dimer, fibrinogen, ferritin, total protein, albumin in correlation with COVID-19 severity." (PMID 36627978, 2022). "Indeed, CRP apheresis can reduce the immune response in COVID-19 patients, as showed in a case series report of seven patients." (PMID 36741367, 2022). "In addition, the COVID-19 patients with high CRP levels had lower levels of anti-spike IgG and neutralizing antibodies at inclusion." (PMID 36685582, 2022). "In addition, D-dimer, LDH, and CRP levels are reported to be potential biomarkers for COVID-19 severity." (PMID 36282812, 2022). "In addition to cytokine storm, COVID-19 patients with severe-to-critical symptoms show elevations in levels of D-dimer, C-reactive protein (CRP), procalcitonin, and ferritin, along with substantial reduction in lymphocytes (B and T cells) and NK cell counts." (PMID 35883618, 2022). "Similarly, the CRP levels showed a 98.5% sensitivity and 94.2% specificity for predicting severe COVID-19, based on an AUC of 0.651 (95% CI: 0.564-0.738) and a cut-off of 154.6 mg/L." (PMID 35464048, 2022).
COVID-19 (continued). "These CO-RADS correlations with CRP and cytokine levels and WBCs and lymphocyte counts may help in the diagnosis and development of strategies for the prevention and therapy of COVID-19-induced pneumonia and lung injury." (PMID 36675695, 2022). "This study suggests that the contemporaneous presence of high levels of LDH, Ferritin, and as expected, CRP, and D-dimer could be considered as potential predictors of COVID-19 severity and death." (PMID 35054342, 2022). "According to these findings, SAA was a better predictor of COVID-19 patient outcome than CRP." (PMID 36465717, 2022). "It was reported that several laboratory tests, such as WBC count, platelet count, and C-reactive protein (CRP), are helpful to predict whether COVID-19 patients are likely to be admitted to the ICU." (PMID 35634446, 2022). "COVID-19 diagnosis was confirmed using RT-PCR testing, and COVID-19 severity was classified using clinical descriptors (respiratory rate, peripheral oxygen saturation score and C-reactive protein levels)." (PMID 36137157, 2022). "Results demonstrated that ALT, CRP, and ferritin values were distributed in normal range in almost all the infected CMs, which are similar as those observed in moderate COVID-19 patients, but are apparently different from severe ones, in which all these indicators increased significantly." (PMID 35903092, 2022). "Additionally, the positive correlation between sACE2 and CRP in diabetic COVID-19 patients denoted a promising role of this marker in the inflammatory status of these patients." (PMID 35455065, 2022). "Notably, elevation of CRP level is one of the main clinical features of patients with COVID-19, and high levels of CRP in the early stage of COVID-19 have been associated with lung damage and disease severity." (PMID 35874670, 2022). "C-reactive protein (CRP) among 14.2% individuals, Erythrocyte Sedimentation Rate (ESR) (7.8%), and SAA (11.4%) (all p < 0.001) were elevated inflammatory biomarkers among hyperregulated cardiac enzymes linked COVID-19 patients." (PMID 36298704, 2022). "Our analysis suggests that inflammatory markers such as the IL-6, CRP and IL-6/Ly ratio could potentially be used as predictors of in-hospital mortality for critical COVID-19 patients." (PMID 36142336, 2022). "Severe COVID-19 in adults is characterized by a hyperinflammatory response that typically occurs in the second week of illness with abnormal biomarkers such as lymphopenia and raised C-reactive protein (CRP) levels." (PMID 35547549, 2022). "Increased serum levels of LDH, fibrinogen and CRP are routinely detected in COVID-19 patients." (PMID 35887555, 2022). "C reactive protein levels were also positively correlated with COVID-19 disease severity." (PMID 35115602, 2022). "Clinical elevation of CRP levels in patients with COVID-19 is one of the characteristics of the disease; however, whether CRP is involved in COVID-19 pathogenesis is unknown." (PMID 35874670, 2022). "Several previous studies have reported CRP as a predictor of COVID-19 severity and mortality." (PMID 36035233, 2022). "The mean concentration of C-reactive protein (CRP) was very high (30.2 ± SD 47.1 mg/l) with significantly higher mean concentration in clinically suspected (33.1 ± SD 47.8 mg/L) compared to confirmed (15.2 ± SD 40.4 mg/L) (p = 0.043) COVID-19 patients." (PMID 35372173, 2022). "Similarly, a retrospective, single-center study of 540 patients from Spain reported that ferritin and high sensitivity C-reactive protein (hs-CRP) were significantly increased in participants who succumbed to COVID-19 during hospital occupancy." (PMID 35974857, 2022). "Inflammatory biomarkers (C reactive protein, ferritin, and procalcitonin), a lung injury biomarker (lactate dehydrogenase), and a coagulopathy biomarker (D-dimer) were elevated in severe COVID-19 patients compared with mild-moderate COVID-19 (p < 0.05) and T2DM patients (p < 0.05)." (PMID 36355535, 2022).
COVID-19 (continued). "Thus, correlations were performed in the current investigation, implying that plasma levels of CRP, SAA, IL-6, CXCL10, VCAM-1, and IL-10, among the linked, exhibit a significant and beneficial association with COVID-19 patient progression." (PMID 35958594, 2022). "Cytokine storm of interleukin (IL)-2, IL-4, tumor necrosis factor-alpha (TNF-α), interferon-gamma (IFN-γ), and C-reactive protein has not been directly associated with COVID-19, whereas IL-6 and IL-10 were found to be COVID-19 severity predictors." (PMID 35054524, 2022). "Additionally, CRP levels in patients who died from COVID-19 were 10-fold higher than those in survivors." (PMID 36231836, 2022). "Vitamin D deficiency was associated with elevated CRP and need for ventilation in hospitalized COVID-19 patients prior to use of dexamethasone but not during the interval of dexamethasone use." (PMID 35276822, 2022). "This assumption might be illustrated by our preliminary observation of an abundant CRP expression in the lung of patients died of COVID-19." (PMID 35402541, 2022). "Interestingly, we found that CRP level was the highest among COVID-19 patients with blood groups A (80%), B (82.7%), and O (80.1%), and the lowest percentage was among patients in blood group AB (71.9%) (p = 0.036)." (PMID 35291516, 2022). "Similar to SARS-CoV infection, the common clinical manifestations of COVID-19 include fever, cough, fatigue, sore throat, dyspnea and pneumonia, with low total lymphocyte count and percentage of T cells, increased C-reactive protein (CRP) concentration and erythrocyte sedimentation rate." (PMID 35109926, 2022). "Additionally, there was a positive correlation between sACE2 and C-reactive protein in diabetic COVID-19 patients, indicating a promising role of this marker in the inflammatory status of these patients." (PMID 35455065, 2022). "Previously, we found that C-reactive protein (CRP, a sensitive inflammatory marker), fibrinogen, D-dimer (a coagulopathy marker), and CD8 T cell count (CD8, an immunological marker) were associated with the progression of COVID-19." (PMID 35310845, 2022). "Finally, broad anti-inflammatory treatment was associated with a reduction in CRP, IL-6 levels as well as length of ICU stay and ventilation-days in critically ill COVID-19 patients." (PMID 35007290, 2022). "Therefore, lymphocytes, CRP, and procalcitonin are important markers of severe COVID-19 illness and their levels must be ascertained to make a positive diagnosis of COVID-19 and other infections." (PMID 34786900, 2022). "Systemic elevations of these cytokines, C-reactive protein (CRP), and ferritin accompanied by lymphopenia are frequently observed in patients with COVID-19 and are also hallmarks of patients with hemophagocytic lymphohistiocytosis, also referred to as macrophage activation syndrome (HLH)." (PMID 35536669, 2022). "Compared to the healthy controls, patients with COVID-19 had significantly higher circulating concentrations of 19 inflammatory mediators, namely interleukins 1α, 2, 6, 7, 8, 10 and 15, CRP, SAA, ICAM-1, VCAM-1, CXCL10, CCL3, CCL26, IFN-γ, TNF-α, bFGF, PlGF and Flt-1 (P < 0.05)." (PMID 35958594, 2022). "According to our results, baseline IP-10 and CRP after 7 days of hospitalization could be useful in driving clinical decisions tailored to the expected disease trajectory in hospitalized COVID-19 patients." (PMID 35242241, 2022). "In addition, they had shorter hospitalization and convalescence periods, lower serum C-reactive protein (CRP), and a reduced risk of developing COVID-19 symptoms such as sore throat, nausea and vomiting, dyspnea, myalgia, cough, weakness, fever, and chills." (PMID 36245547, 2022). "In the present study, the relationship between a poor prognosis and adropin levels in diabetic patients with COVID was investigated by measuring serum adropin levels and levels of D-dimer, C-reactive protein (CRP), and ferritin, which are considered prognostic factors for COVID-19." (PMID 35703530, 2022).
COVID-19 (continued). "The upregulation of C reactive protein (CRP) that has been reported in COVID-19 patients might be an indication of excessive inflammatory stress and contribute to severe illness or even death." (PMID 35794133, 2022). "To evaluate the health status of pregnant women affected by COVID-19 we decided to analyse the white blood cells; in addition, we assessed the levels of c-reactive protein (CRP) to understand the severity of the inflammatory state caused by the coronavirus infection." (PMID 35408809, 2022). "For COVID-19-positive patients alone, the time between the disease onset and admission to the hospital (days) was the most impactful feature, individually predicting ICU admission risk with 73.9% sensitivity, while CRP predicted with 64.29% sensitivity." (PMID 36140545, 2022). "The validity of CRP as a significant predictor of the outcome in COVID-19 was confirmed many times." (PMID 35407379, 2022). "Furthermore, IL-1β mediates Il-6 synthesis, a key proinflammatory cytokine in COVID-19 cytokine storm and a potent inducer of CRP." (PMID 36422492, 2022). "We examined whether TNF receptors (TNFRs: TNFR1, TNFR2) and progranulin (PGRN) levels, in addition to interleukin 6 (IL-6) and C-reactive protein (CRP), are associated with mortality or disease severity in COVID-19 patients." (PMID 36219652, 2022). "However, GLA-TBR was moderately associated with high sensitivity CRP and with days from admission to FDG PET/CT in COVID-19 patients." (PMID 36341267, 2022). "An elevated CRP may reflect elevated IL-6 levels, and both of these can perpetuate the inflammatory diabetogenic process of COVID-19 as well." (PMID 36498589, 2022). "Moreover, the authors observed inverse correlations between the level of T-helpers and the concentrations of D-dimer, ferritin, and CRP in the serum of COVID-19 patients." (PMID 35632823, 2022). "CRP is widely used as a marker for inflammation in GvHD, sepsis, and COVID-19." (PMID 36181766, 2022). "Ferritin was a less potent mediator than hs-CRP of the effect of sex on COVID-19 outcomes, though the mediation effect was statistically significant and may be clinically important." (PMID 35548417, 2022). "In COVID-19 patients, comorbidity, age, and male sex were the major predictors of death in two large studies, and three meta-analyses found CRP and NLR as predictors of severity and intra-hospital death as well." (PMID 35204633, 2022). "For example, CRP levels, typically elevated in bacterial infections, may be elevated in COVID-19 cases." (PMID 36182905, 2022). "In the prospect of anticipating COVID-19’s unfavorable progression, our study aimed to determine whether C- Reactive Protein can be used as a reliable prognostic indicator to that effect." (PMID 36451818, 2022). "CRP levels were higher in COVID-19 patients than the non-COVID-19 group." (PMID 36601011, 2022). "However, prothrombin time and C-reactive protein levels were high in ICU COVID-19 patients and they can be used as a biomarker to severity of the disease." (PMID 35168674, 2022). "Sera biomarkers that indicate cardiac damage, inflammation and thrombosis such as troponin T and I, CRP, tumor necrosis factor (TNF), IL-1β and IL-6 have been found to be associated with increased mortality as well as being elevated in males with COVID-19 compared to females." (PMID 36292038, 2022). "Zhong Nanshan's team reported in the literature that 63.4% of COVID-19 patients had a fever and lung abnormalities in chest CT scans; experimental studies have shown that patients with COVID-19 have lymphocyte reduction and increased levels of reactive protein (CRP)." (PMID 35818408, 2022). "Because CRP was greater in patients with COVID-19 in this study, “which is a factor in the intensity of inflammation,” the severity of the condition may have been higher in patients with COVID-19." (PMID 35251166, 2022).